CGAS (cyclic GMP-AMP synthase)
Diseases named in the same sentence as CGAS in open-access papers (continued):
Sharing a sentence is not in itself a finding about the gene and the disease.
tumor (continued). "Understanding these dynamics is crucial for developing effective strategies that leverage the anti-tumor potential of the cGAS-STING pathway in macrophages while minimizing the risk of enhancing tumor-promoting activities." (PMID 38523155, 2024). "We show that the elevated production of miR-25 and miR-93 within hypoxic GBM cells leads to EV-shuttled transfer of these miRNAs to normoxic macrophages; this resulted in suppression of cGAS expression, and a deficient response to tumor-cell derived DNA." (PMID 38389103, 2024). "It was observed that PTT induced immunogenic cell death (ICD), releasing damage-associated molecular patterns (DAMPs) and tumor-associated antigens (TAAs), with mt-DNA in DAMPs sensed by cyclic GMP-AMP synthase (cGAS)." (PMID 38673726, 2024). "In human lung adenocarcinoma, the loss of cGAS has been shown to enhance tumor growth, while high expression of STING is associated with poor prognosis in colorectal cancer patient subgroups." (PMID 39295867, 2024). "This study shows that innate immune signaling via cGAS-STING or RLR-MAVS regulates tumor-associated macrophage tissue residency through activation of the TBK1-Zyxin axis." (PMID 39304793, 2024). "The cGAS-STING signaling pathway has been implicated in promoting tumor proliferation and metastasis." (PMID 39420203, 2024). "We also assessed the association of tumor cell-intrinsic expression of cGAS–STING with MMR status in GC." (PMID 39242811, 2024). "Our study revealed an aberrant therapeutic mechanism underlying two tumor defects, cGAS and NF-κB p65, and provided an alternative IDTR approach based on oncolytic adenovirus and antisense oligonucleotides for efficient therapeutic efficacy in tumors." (PMID 38782895, 2024). "Deficiencies in the cGAS-STING pathway reduce tumor immunogenicity, lowering the efficacy of immune checkpoint inhibitors." (PMID 40018367, 2024). "Inflamed cells display evidence of heightened cGAS/STING signaling which we demonstrate is sufficient to cause tumor cell resistance to chemotherapy." (PMID 38355954, 2024). "In conclusion, we have demonstrated that the tumor cell-intrinsic cGAS–STING pathway is associated with increased infiltration of CD8+ T cells in dMMR/MSI-H GC." (PMID 39242811, 2024). "Active cGAS-STING signaling has also been linked with the production of certain chemokines that recruit T cells to the tumor site such as CXCL10, as well as induction of T-cell stemness." (PMID 38660307, 2024). "For instance, in several mouse tumor models, tumors exhibit accelerated growth in mice deficient in cGAS or STING, concomitant with a diminished functionality of DCs." (PMID 38512518, 2024). "We then assessed IFN-β production by DCs after coculture with MA9-OVA cells pretreated with LD2 and observed increased IFN-β production, an effect abolished by cGAS KO, suggesting that tumor cGAS activation underlies type I IFN signaling in DCs." (PMID 38413714, 2024). "In some tumor types, tumor-associated immune escape mechanisms inhibit the activation of the cGAS-STING pathway." (PMID 39445027, 2024). "Under X-rays exposure, ICD of the tumor cells would be caused, and a plenty of DNA was damaged and leaked into the cytoplasm, further activating the cGAS-STING pathway." (PMID 38831378, 2024). "The cGAS-STING signaling pathway has also been implicated in the priming of anti-tumor T-cell response and the trafficking of immune cells to the TME." (PMID 38921005, 2024). "A study evaluating The Cancer Genome Atlas (TCGA) and other human tumor genome databases revealed that tumors frequently contain loss-of-function mutations as well as epigenetic silencing of cGAS and STING." (PMID 38659582, 2024). "In serial sections of HCC samples from the same patient, high tumor LRRC8C expression was associated with high STING expression in CD31+ vascular endothelial cells in either high or low tumor cGAS expression group." (PMID 38177099, 2024).
tumor (continued). "A pan‐cancer analysis of more than 10,000 samples from the TCGA database revealed that inactivating mutations and genomic loss of cGAS or STING occurred in less than 1% of tumor types." (PMID 38525112, 2024). "cGAS/STING activation occurs when damage-associated molecular patterns (DAMPs) are detected in the tumour microenvironment (TME), often induced by chemotherapy or radiotherapy." (PMID 39403376, 2024). "Studies utilizing a mouse tumor model of T cell reinfusion confirm that deficiencies in cGAS or STING within CD8+ T cells diminish their antitumor efficacy." (PMID 39834588, 2024). "The combination of IR and DNA-PKcs inhibition was shown to enhance cytosolic dsDNA and tumor-associated type I IFN signaling independently of cGAS and STING." (PMID 37420037, 2023). "We finally examined the association between the expression of cGAS-STING in tumor cells and clinical outcomes in patients with pMMR/MSS CRC." (PMID 37345163, 2023). "We also examined the association between the expression of cGAS-STING in tumor cells and the infiltrations of CD8+ T cells and CD4+ T cells in pMMR CRC." (PMID 37345163, 2023). "In cancers, intercellular communication of cGAS-STING signaling connects the tumor microenvironment and pathogenic, immune, and stromal cells, thus promoting or compromising various immune responses and substantially altering disease progression." (PMID 36861445, 2023). "In this review, we will discuss how a deficiency in DDR affects anti-tumor immunity, highlighting the cGAS-STING axis as an important link." (PMID 36900418, 2023). "We also examined the association between the expression of cGAS-STING in tumor cells and the infiltrations of Treg cells (Foxp3+ cells) in pMMR CRC by IHC." (PMID 37345163, 2023). "In this review, we summarize the latest mechanism and roles of the cGAS-STING pathway in tumor development and highlight associated treatments in combination with the latest research." (PMID 37153627, 2023). "Neurofibroma protein 2 (NF2), a classical tumor suppressor that controls tumor growth and regulates angiogenesis in the tumor microenvironment, has been reported to regulate cGAS-STING signaling through NF2 mutation mediated-LLPS." (PMID 36860877, 2023). "In light of the bridging role of STING signaling between innate and adaptive immunity in response to DAMPs and PAMPs, a wealth of studies have reported the underlying mechanisms by which the cGAS–STING signaling pathway controls tumor progression." (PMID 37560754, 2023). "In the clinic, downregulation of cGAS or STING in dMMR tumors is associated with poor prognosis since it decreases DNA-sensing-mediated anti-tumor immune surveillance." (PMID 37122745, 2023). "In this study, we identify a role of tumor-intrinsic TRABID in regulating TME by showing that TRABID deficiency induces micronuclei to activate cGAS/STING pathway, thereby shaping an anti-tumor immune microenvironment." (PMID 37237031, 2023). "A significant association was observed between the location of tumor and the proportion of cGAS/STING positivity in pMMR/MSS CRC (p < 0.05)." (PMID 37345163, 2023). "The intracellular cyclic GMP-AMP (cGAMP) synthase (cGAS) stimulator of the interferon gene (STING) pathway senses tumor-associated DNA." (PMID 37174127, 2023). "We next examined the association between the expression of cGAS-STING in tumor cells and clinico-pathological characteristics of patients with pMMR CRC." (PMID 37345163, 2023). "Intriguingly, a recent publication implied a role of ATRX in the cytosolic cGAS-STING DNA sensing pathway in ALT positive tumor cells, by showing that loss of both STING and ATRX expression is responsible for a defective DNA sensing in ALT cells." (PMID 35939517, 2022). "Using preclinical models, we demonstrated constitutive activation of the cGAS-STING pathway in DNA-repair-deficient tumours to be the underlying mechanism for this innate immune response." (PMID 34728791, 2022).
tumor (continued). "Taken together, this demonstrates how data-driven cGAS-STING grouping associates with relevant tumor biology with potential prognostic relevance." (PMID 36923311, 2022). "Detection of such DNA by cGAS is suggested to be an immune-surveillance mechanism, clearing potential oncogenic mutated cells and suppressing tumor progression in the early stage." (PMID 35734577, 2022). "MLH1-deficient tumor cells accumulate cytoplasmic DNA to activate the cGAS-STING pathway, which sensitizes MLH1-deficient tumors to immunotherapy by promoting initiation and infiltration of antitumor CD8+ T cells." (PMID 36591232, 2022). "Loss of cGAS-STING signaling facilitates tumor cells to escape immune surveillance, thereby promoting carcinogenesis and resistance towards immunotherapy." (PMID 35327359, 2022). "In murine and human cancer cell lines, ATM deficiency induces ISG expression and tumor infiltration of immune cells in a cGAS/STING-dependent manner." (PMID 36276148, 2022). "Correctively, antitumor immune therapy requires activating APCs by the cGAS/STING pathway as well as enhancing tumor-associated antigen presentation to T cells to improve efficiency." (PMID 35265630, 2021). "On the other hand, inactivation of cGAS signaling causes deficiency to sense and clear the viral and bacterial infection and creates a tumor-prone immune microenvironment to facilitate tumor evasion of immune surveillance." (PMID 33927185, 2021). "Downregulation of cGAS-STING signaling has been associated with poor prognosis in several tumor types." (PMID 34625078, 2021). "Activation of the cyclic GMP-AMP synthase (cGAS) mediates classical DNA sensing, is involved in genome instability, and is linked to various tumor development or therapy." (PMID 37305397, 2021). "The effect of tumor immunotherapy depends on expression of tumor-associated antigens and partially on antigen presentation; the cGAS/STING pathway has been used in combination immunotherapy in some tumors due to its enhancement of APC function." (PMID 35265630, 2021). "These all indicate the potential anti-tumor activation through a cGAS-STING-STAT1-mediated ISGs-involved pathway upon the loss of both POLQ and FANCD2 in ESCC." (PMID 34206946, 2021). "Upregulation of PD-L1 is primarily driven by tumour-associated inflammation via the cGAS-STING pathway, reflecting the status of TME." (PMID 34572747, 2021). "For example, it has already been demonstrated that cGAS-STING pathway is deficient in different tumor cell lines due to the inhibition of cGAS and/or STING expression by a process of DNA hypermethylation." (PMID 34341449, 2021). "The activation of cGAS/STING-signaling mediates immunogenic effects in dying tumor cells caused by radiotherapy, chemotherapy (including gemcitabine), adenoviral vectors, or oncolytic components." (PMID 34071585, 2021). "The instability of the tumor genome also causes the up-regulation of the cGAS-STING pathway 44,45, which in turn activates the innate immune response." (PMID 34158843, 2021). "The cGAS-STING pathway can be activated by tumor cell-derived DNA, and STING- or IRF3-deficient mice showed defects in priming CD8+ T cells and tumor control." (PMID 33633744, 2020). "Hypo EGFR TKI can induce hypoptosis in tumor cells, releasing tumor-derived danger-associated molecular patterns (DAMPs), that can activate cGAS-STING and Toll-like receptors (TLR)-Myd88, that are essential for type I interferon production." (PMID 32516941, 2020). "Similar results were obtained using cGAS-deficient DCs, suggesting cGAS-sensing of tumor-derived dsDNA within DCs was involved and potentially important for mediating the capacity of DCs to stimulate CD8+ T cells." (PMID 33238631, 2020). "Dying or damaged cancer cell–derived DNA can act as a damage-associated molecular pattern sensed by cytosolic cGAS-STING machinery in tumor-associated CD8α+ dendritic cells (DCs), leading to the production of type I IFNs." (PMID 31601678, 2019).
tumor (continued). "This route to cGAS activation by micronuclei was recently implicated in the response to tumours to DNA damaging drugs and radiation." (PMID 29142107, 2017). "cGAS/STING is a PRR that recognizes pathogenic cytosolic DNA, and DNA from dying tumor cells can be a ligand for cGAS." (PMID 27854240, 2016). "Furthermore, phagocytosis of tumor-derived damage-associated molecular patterns by tumor-associated macrophages (TAMs) triggered the activation of cGAS-STING signaling and promoted M1 polarization of TAMs without obvious macrophage cell death." (PMID 41782113, 2026). "However, the mechanisms underlying the downregulation of tumor cell-intrinsic cGAS–STING expression in CRC remain poorly understood." (PMID 40451897, 2025). "The Initial Alarm: DNA Sensing and cGAMP Production: cGAS functions as a cytosolic DNA sensor that recognizes aberrant double-stranded DNA (dsDNA) derived from tumor-associated sources, including micronuclear DNA, mitochondrial DNA (mtDNA), neutrophil extracellular traps (NETs), and exosomal DNA." (PMID 41573551, 2025). "The enhanced anti-tumor activity was associated with the activation of the cGAS-STING pathway." (PMID 41142804, 2025). "However, to evade this DNA sensing mechanism, tumor cells often acquire mutations to disrupt the cGAS‐STING axis and induce mutations or deletions in type I IFNs motif." (PMID 40672434, 2025). "Since downregulated tumor cell-intrinsic cGAS–STING expression is associated with decreased frequency of CD8+ TILs, targeting CAFs could represent a novel therapeutic strategy to improve patient outcomes in CRC." (PMID 40451897, 2025). "Emerging evidence indicates that deficiencies in DNA repair response in tumor cells can active the cGAS‐STING and downstream type I IFN signaling, resulting in the transformation of immune “cold” cancers (poor immune cell infiltration) to “hot” cancers, which is in line with our findings." (PMID 40126333, 2025). "We next asked whether the suggested improved uptake of tumor cell debris and activation of the cGAS-STING-IFN-I pathway in vivo resulted from the loss of cell intrinsic FXa-PAR2 signaling." (PMID 40694429, 2025). "The regulatory mechanism underlying the CAF-induced downregulation of tumor cell-intrinsic cGAS–STING expression in CRC in the present study remains unclear." (PMID 40451897, 2025). "However, in the treatment of some tumors, the rational use of inhibitors to inhibit the cleavage activity of endo/exonucleases can cause genomic instability in tumor cells, thereby activating the cGAS-STING pathway and enhancing the efficacy of immunotherapy." (PMID 39759116, 2025). "In BRCA1-deficient TNBC, PARP inhibitor olaparib activates the cGAS/STING pathway in tumor cells, leading to dendritic cell-dependent CD8+ T cell recruitment and antitumor immunity, with more pronounced effects in HR-deficient models and demonstrated STING pathway dependency." (PMID 41573551, 2025). "Moreover, the activation of the cGAS-STING pathway is also associated with the remodeling of the tumor microenvironment and the enhancement of drug penetration." (PMID 40567603, 2025). "Additionally, we evaluated the association between the tumor cell-intrinsic cGAS–STING expression and CD8+ T cell-infiltration in both pMMR/EBV (−) and dMMR GCs." (PMID 39242811, 2024). "MPM is strongly responsive to synthetic activators of cGAS/STING pathway that increase the production of CXCR3 in tumor cells and cancer-associated fibroblasts, resulting in the recruitment and activation of NK cells and mesothelin-targeted chimeric antigen receptor (CAR)-NK cells." (PMID 39709435, 2024). "Notably, as observed in cell lines, cGAS deficiency also conferred resistance to 5-FU in the AOM/DSS tumour model." (PMID 39080411, 2024). "Additionally, cGAS/STING signalling influences the polarization of tumour-associated macrophages (TAMs), shifting them from an immunosuppressive M2-like phenotype to a pro-inflammatory M1-like phenotype." (PMID 39403376, 2024).
tumor (continued). "However, when cancer cells transition from the dormant phase to the proliferative phase, STING activity increases, making cancer cells more susceptible to immune system attacks, and prolonged cGAS–STING activation promotes tumor metastasis." (PMID 39090094, 2024). "Third, due to the complexity of molecular pathways in tumor biology, the interaction between cGAS-STING and others may cause undetected influence on PCa, making it difficult to elucidate the detailed impacts induced by a single mechanism." (PMID 38877472, 2024). "In conclusion, immunosuppressive effects of PTEN loss through the cGAS-STING pathway in GBM tumours could be shown in this study." (PMID 38214828, 2024). "Genomic tumor alterations, DNA lesions induced by radio‐chemotherapy, DDRi, alone or in combination can cause accumulation of cytosolic DNA fragment able to activate the cGAS‐STING pathway and to trigger and modulate antitumor‐immune response." (PMID 39492835, 2024). "Thus, the inhibition of the cGAS-STING pathway in macrophages by hypoxic GBM EVs with their miR-25/93 cargo elucidates an underlying mechanism for impaired anti-tumor immune functions seen in hypoxic GBM tumors." (PMID 38389103, 2024). "The unique characteristics of cGAS-STING genes in BLCA are hypothesized to be associated with the particular tumor microenvironment." (PMID 38240703, 2024). "In a subset of gastroesophageal adenocarcinoma (GOA) patients, chemotherapy promotes antitumour inflammation within the TME by reorganizing the T-cell compartment and inducing innate signalling pathways, including cGAS/STING in tumour cells, which is associated with chemotherapy response." (PMID 38744099, 2024). "This contrasted with ccGAS knockdown inhibiting cancer cell growth in vitro, suggesting cGAS deficiency may promote in vivo tumour growth by relieving anti-tumourigenic effects through the cGAS–STING pathway." (PMID 39080411, 2024). "Does PTEN mutations effect tumour immunogenicity through the cGAS-STING pathway?" (PMID 38214828, 2024). "Our study revealed that the utilization of molecular subtypes and genetic risk score that associated with the cGAS-STING pathway could assist clinicians in identifying PCa patients who harbor unfavorable tumor feature." (PMID 38877472, 2024). "The results showed that BMDCs pre-cultured with Ogt+/+ or Ogt−/− B16-OVA tumor cells supernatant provided a potent activated signal for optimal single epitope-specific T cell proliferation, while cGAS or STING deficiency in Ogt−/− tumor cells diminished such effects." (PMID 38168435, 2024). "Activation of the cGAS-STING pathway has been associated with the promotion of anti-tumor immunity." (PMID 38177099, 2024). "Additionally, our study revealed that POLE mutations significantly enhanced cGAS expression level in primary human cells and tumor specimens." (PMID 38238314, 2024). "DNA derived from chemotherapeutics-killed tumor cells is one of the most important damage-associated molecular patterns that can activate the cGAS-STING (cyclic GMP-AMP synthase—stimulator of interferon genes) pathway in antigen-presenting cells (APCs) and promote antitumor immunity." (PMID 37391428, 2023). "cGAS/STING activation is linked to the induction of anti-tumor immune responses." (PMID 37237031, 2023). "Additionally, due to the loss of the expression of cGAS, several tumor cell lines are defective in producing IFNs and cytokines after stimulating by DNA or infecting by viruses." (PMID 37834184, 2023). "Next, we determined whether TRABID deficiency-induced activation of cGAS/STING pathway could elicit anti-tumor responses by shaping tumor immune microenvironment." (PMID 37237031, 2023). "Then, in a second part we detailed important notions suggesting that altered cancer cell metabolism, specific oncogenic signaling, tumor suppressor loss as well as tight control of the cGAS/STING pathway in the cancer cells can be associated with resistance to immune checkpoint blockade." (PMID 37180110, 2023).